DRD2 (dopamine receptor D2)
Description:
Dopamine receptor whose activity is mediated by G proteins which inhibit adenylyl cyclase. Positively regulates postnatal regression of retinal hyaloid vessels via suppression of VEGFR2/KDR activity, downstream of OPN5 (By similarity).
Synonyms: D2R; D2DR
Tractability: Small molecule: an approved drug acts on it; a structure with a bound ligand is known; a high-quality ligand is known; it belongs to a druggable protein family. Antibody: UniProt places it where antibodies can reach, with high confidence; its Gene Ontology location is reachable by antibodies, with high confidence; UniProt predicts a signal peptide or a membrane-spanning region. PROTAC: a small molecule that binds it is known. Other modalities: an approved drug acts on it.
Target class: Small molecule receptor (family A GPCR); Dopamine receptor; Family A G protein-coupled receptor; Monoamine receptor; Membrane receptor
Chemical probes: CHEMBL3344470, FLUSPIRILENE, ML321 (high quality)
Safety:
Unwanted effects reported when the protein is acted on. In parentheses: how it was acted on, where the effect was seen, and who reports it.
confusion (Lynch et al. (2017): activation, acute dosing, renal, central nervous system, cardiovascular, gastrointestinal; Bowes et al. (2012): activation, cardiovascular system, central nervous system, endocrine)
decreased heart rate (Bowes et al. (2012): activation, cardiovascular system, central nervous system, endocrine; Lynch et al. (2017): activation, acute dosing, renal, central nervous system, cardiovascular, gastrointestinal)
drowsiness (Bowes et al. (2012): inhibition and activation, cardiovascular system, central nervous system, endocrine; Lynch et al. (2017): inhibition, acute dosing and activation, acute dosing, renal, central nervous system, cardiovascular, gastrointestinal)
hallucinations (Bowes et al. (2012): activation, cardiovascular system, central nervous system, endocrine; Lynch et al. (2017): activation, acute dosing, renal, central nervous system, cardiovascular, gastrointestinal)
orthostatic hypotension (Lynch et al. (2017): inhibition, acute dosing, renal, central nervous system, cardiovascular, gastrointestinal; Bowes et al. (2012): inhibition, cardiovascular system, central nervous system, endocrine)
catalepsy (inhibition, acute dosing; renal, central nervous system, cardiovascular, gastrointestinal; source: Lynch et al. (2017))
decreased blood pressure (activation, acute dosing; renal, central nervous system, cardiovascular, gastrointestinal; source: Lynch et al. (2017))
decreased body temperature (activation, acute dosing; renal, central nervous system, cardiovascular, gastrointestinal; source: Lynch et al. (2017))
decreased convulsions (activation, acute dosing; renal, central nervous system, cardiovascular, gastrointestinal; source: Lynch et al. (2017))
decreased gastrointestinal transit (activation, acute dosing; renal, central nervous system, cardiovascular, gastrointestinal; source: Lynch et al. (2017))
decreased locomotor activity (inhibition, acute dosing; renal, central nervous system, cardiovascular, gastrointestinal; source: Lynch et al. (2017))
decreased pain (activation, acute dosing; renal, central nervous system, cardiovascular, gastrointestinal; source: Lynch et al. (2017))
decreased pituitary hormone secretion (activation, acute dosing; renal, central nervous system, cardiovascular, gastrointestinal; source: Lynch et al. (2017))
decreased pituitary hormone secretions (activation; cardiovascular system, central nervous system, endocrine; source: Bowes et al. (2012))
decreased/increased Locomotor activity (activation, acute dosing; renal, central nervous system, cardiovascular, gastrointestinal; source: Lynch et al. (2017))
drug abuse/dependence (activation, acute dosing; renal, central nervous system, cardiovascular, gastrointestinal; source: Lynch et al. (2017))
emesis (activation; cardiovascular system, central nervous system, endocrine; source: Bowes et al. (2012))
fainting (activation, acute dosing; renal, central nervous system, cardiovascular, gastrointestinal; source: Lynch et al. (2017))
fibrotic valvular heart disease (activation, chronic dosing; renal, central nervous system, cardiovascular, gastrointestinal; source: Lynch et al. (2017))
heart failure (activation, chronic dosing; renal, central nervous system, cardiovascular, gastrointestinal; source: Lynch et al. (2017))
increased blood pressure (inhibition, acute dosing; renal, central nervous system, cardiovascular, gastrointestinal; source: Lynch et al. (2017))
increased convulsions (inhibition, acute dosing; renal, central nervous system, cardiovascular, gastrointestinal; source: Lynch et al. (2017))
increased gastrointestinal motility (inhibition; cardiovascular system, central nervous system, endocrine; source: Bowes et al. (2012))
increased gastrointestinal transit (inhibition, acute dosing; renal, central nervous system, cardiovascular, gastrointestinal; source: Lynch et al. (2017))
increased sodium excretion (activation; cardiovascular system, central nervous system, endocrine; source: Bowes et al. (2012))
increased urinary sodium excretion (inhibition, acute dosing and activation, acute dosing; renal, central nervous system, cardiovascular, gastrointestinal; source: Lynch et al. (2017))
increased urine excretion (inhibition, acute dosing; renal, central nervous system, cardiovascular, gastrointestinal; source: Lynch et al. (2017))
stereotypy (activation, acute dosing; renal, central nervous system, cardiovascular, gastrointestinal; source: Lynch et al. (2017))
syncope (activation; cardiovascular system, central nervous system, endocrine; source: Bowes et al. (2012))
vomiting (activation, acute dosing; renal, central nervous system, cardiovascular, gastrointestinal; source: Lynch et al. (2017))
and 11 more effects
Gene: Protein-coding gene on chromosome 11 (113,409,605 to 113,476,402, reverse strand). Ensembl gene ENSG00000149295.
Subcellular location: Cell membrane; Golgi apparatus membrane
Pathways (Reactome):
Signal Transduction: Dopamine receptors
Gene Ontology:
Molecular function: dopamine neurotransmitter receptor activity; dopamine neurotransmitter receptor activity, coupled via Gi/Go; G-protein alpha-subunit binding; heterotrimeric G-protein binding; identical protein binding; protein binding; G protein-coupled receptor activity; dopamine binding; ionotropic glutamate receptor binding; protein-containing complex binding; signaling receptor binding
Biological process: adenylate cyclase-inhibiting dopamine receptor signaling pathway; arachidonate secretion; negative regulation of protein secretion; phospholipase C-activating dopamine receptor signaling pathway; positive regulation of cytokinesis; positive regulation of glial cell-derived neurotrophic factor production; response to histamine; adenohypophysis development; adult walking behavior; associative learning; axonogenesis; behavioral response to cocaine; behavioral response to ethanol; beta-arrestin-dependent dopamine receptor signaling pathway; branching morphogenesis of a nerve; cerebral cortex GABAergic interneuron migration; circadian regulation of gene expression; dopamine metabolic process; excitatory postsynaptic potential; hyaloid vascular plexus regression; intracellular protein localization; locomotory behavior; negative regulation of blood pressure; negative regulation of cell migration; negative regulation of cell population proliferation; and 78 more
Cellular component: ciliary membrane; cilium; G protein-coupled receptor complex; Golgi membrane; non-motile cilium; plasma membrane; axon; dendrite; glutamatergic synapse; postsynaptic membrane; presynaptic membrane; acrosomal vesicle; axon terminus; dendritic spine; dopaminergic synapse; endocytic vesicle; GABA-ergic synapse; lateral plasma membrane; membrane; perikaryon; sperm flagellum; synaptic vesicle membrane
Genetic constraint (gnomAD): Loss-of-function variants: 8 observed, 38.83 expected, observed/expected ratio (o/e) 0.21, 90% interval 0.12 to 0.37. The upper end of that interval is the gene's LOEUF score, 0.37, which puts it in group 1 of 6, group 1 being the genes least tolerant of losing a copy. Missense variants: 403 observed, 636.32 expected, observed/expected ratio (o/e) 0.63, 90% interval 0.58 to 0.69. Synonymous variants: 230 observed, 249.12 expected, observed/expected ratio (o/e) 0.92, 90% interval 0.83 to 1.03.
Homologues: Orthologues: chimpanzee DRD2 (100% identical), macaque DRD2 (99% identical), pig DRD2 (97% identical), dog DRD2 (97% identical), guinea pig DRD2 (96% identical), rabbit DRD2 (96% identical), rat Drd2 (96% identical), mouse Drd2 (96% identical), tropical clawed frog drd2 (76% identical), zebrafish drd2b (70% identical), zebrafish drd2a (68% identical), Caenorhabditis elegans ser-5 (22% identical). Paralogues in human: ADRA2A (32% identical), ADRA2B (29% identical), ADRA2C (29% identical), ADRA1B (29% identical), ADRA1A (27% identical), ADRA1D (27% identical), ADRB2 (25% identical), ADRB3 (24% identical), ADRB1 (24% identical), GPR101 (16% identical), OR56A3 (12% identical), OR56A4 (12% identical), and 6 more.
Diseases named in the same sentence as DRD2 in open-access papers:
DRD2 is named in the same sentence as 334 diseases in open-access papers, as found by Europe PMC text mining. Sharing a sentence is not in itself a finding about the gene and the disease. The quoted sentences say what the papers report.
schizophrenia (437 papers, 2007 to 2026). A major psychotic disorder characterized by abnormalities in the perception or expression of reality. "Research has shown that miR-9-5p is not only involved in the regulation of DRD2 but also interacts with other genes associated with schizophrenia risk." (PMID 40779062, 2026). "For example, DRD2 linked all antipsychotics to schizophrenia; however, removing DRD2 from the drug set still revealed significant enrichment for other schizophrenia medication targets, including off-targets." (PMID 40379965, 2025). "For example, the first generation antipsychotic DRD2 antagonist Haloperidol, was also linked to schizophrenia by the off-target GRIN2A, which encodes a subunit of the glutamatergic NMDA receptor involved in synaptic plasticity and learning." (PMID 40379965, 2025). "Traditional DRD2 antagonists, such as Haloperidol and risperidone, are known for their efficacy in treating schizophrenia but are often associated with severe side effects, including extrapyramidal symptoms and metabolic disturbances." (PMID 40283994, 2025). "Possible effects of DRD2 gene polymorphisms, which are thought to be a schizophrenia susceptibility gene, and possible side effects in treatment are among the issues that have attracted attention recently." (PMID 38899233, 2024). "An independent GWAS that aimed at identifying genetic loci associated with Schizophrenia, a psychiatric disorder in which patients display social withdrawal, similarly identified DRD2." (PMID 38114631, 2024). "COMT rs4680 polymorphism also appears to interact with DRD2 rs2283265 in influencing the risk of hypofrontality (an endophenotype often associated with schizophrenia), as observed in an Australian study." (PMID 39595853, 2024). "In females with schizophrenia, we have found that functional polymorphism rs1799732 of the DRD2 gene is associated with MetS." (PMID 38540239, 2024). "In the literature, there is a study evaluating DRD2-141C polymorphisms in SD in patients with schizophrenia." (PMID 38899233, 2024). "The cell adhesion molecule close homolog of L1 (CHL1) contributes to dopaminergic system development, and CHL1 and the dopamine receptor D2 (D2R) are associated with mental disorders like schizophrenia, addiction, autism spectrum disorder and depression." (PMID 38025382, 2023). "The voxel‐level uncorrected papers often investigated uncommon disease/population groups, such as DRD2 rs1076560 polymorphism (risk factor for schizophrenia), children with developmental coordination disorder, and patients with Tourette Syndrome." (PMID 36479854, 2023). "The DRD2 gene codes for the D2 dopamine receptor, which is the primary site of the therapeutic action of antipsychotics and has been implicated in the pathophysiology of schizophrenia." (PMID 36980961, 2023). "Recently, an association study in Mexican schizophrenia patients related the single-nucleotide polymorphism A-241G of the DRD2 gene and the Met/Met allele of COMT and Ser/Gly allele of DRD3 genes with resistance to treatment." (PMID 36979877, 2023). "The large-scale genome-wide association study from the Psychiatric Genomics Consortium (PGC) has found that the top single-nucleotide polymorphism (SNP), i.e., rs2514218, associated with schizophrenia was located about 47 kb upstream of the DRD2 gene sequence." (PMID 36979877, 2023). "Evidence suggested that haplotype polymorphisms of Taq1A and -141c Ins/Del DRD2 genes contributed to DRD2 antagonist resistance, especially linked to anxiety and depressive symptoms in schizophrenia." (PMID 36313375, 2022). "The present study examined the association of two polymorphisms of the DRD2 gene with metabolic syndrome in patients with schizophrenia." (PMID 35893053, 2022). "We aimed to investigate the relationship between the DRD2 gene network and in vivo striatal dopaminergic function, which is a phenotype robustly associated with psychosis and schizophrenia." (PMID 35871219, 2022).
schizophrenia (continued). "The polymorphism of DRD2 (C957T) has been known to be associated with schizophrenia, while the result seems inconsistent in different populations." (PMID 35990059, 2022). "The dopamine receptor type 2 gene (DRD2) polymorphism was also known as one of the risk variants for schizophrenia." (PMID 35990059, 2022). "This cross-sectional study of 471 patients with schizophrenia examined the possible association between two variants (rs1799732, rs4436578) of the DRD2 gene and the presence of the metabolic syndrome." (PMID 35893053, 2022). "The genotypes (p = 0.012) and alleles (p = 0.004) of the polymorphic variant rs1799732 of the DRD2 gene are associated with the development of drug-induced MetS in women with schizophrenia." (PMID 35893053, 2022). "Due to previous associations of DRD2 splice variants with schizophrenia and its addiction-like phenotypes and tissue-specific expression, it will be interesting to explore this dopaminergic variant in the context of the present study." (PMID 35405990, 2022). "miR-9-5p, miR-485-5p, and miR-137 regulate schizophrenia risk genes and miR-9-5p targets the DRD2, a drug-target in schizophrenia." (PMID 36359330, 2022). "DRD2 is an important gene in the dopamine pathway, and genetic variations of DRD2 are involved in schizophrenia and susceptibility to post-traumatic stress disorder." (PMID 34492034, 2021). "DRD2 is a well-established psychiatric risk gene, and has shown robust association with multiple psychiatric disorders, including schizophrenia, MD, alcohol dependence, and various mental health measures, such as neuroticism, well-being, and cigarette smoking." (PMID 34603368, 2021). "Polymorphic variants in SLC6A4, MAOA, DRD4, and DRD2 have shown statistical associations with major depressive disorder, anti-social behaviour, schizophrenia, and bipolar disorder." (PMID 33809805, 2021). "Another study on sexual dysfunction in male schizophrenia showed that correlation between two polymorphisms in the genes for the DRD2 and scores on questionnaires for erectile and sexual dysfunction were studied." (PMID 32161689, 2020). "DRD2 has long been a candidate gene for schizophrenia and other psychiatric disorders and was recently implicated in the list of genome-wide significant loci in the Psychiatric Genomics Consortium meta-analysis of schizophrenia genome-wide studies." (PMID 31040383, 2020). "This study can provide references for the association between DRD2 promoter region and schizophrenia in the Han population in north China." (PMID 30657260, 2019). "It targets DRD2, linked to bipolar disorder, schizophrenia, depressive disorder, Parkinson’s disease and attention deficit hyperactivity disorder." (PMID 31481665, 2019). "Prior to this, the role of dopamine receptor D2 (DRD2) gene promoter polymorphisms and schizophrenia has been studied extensively, but there are still some uncertainties about these associations." (PMID 30657260, 2019). "DRD2 splice variants have previously been implicated with schizophrenia and impaired cognitive function in humans." (PMID 31292793, 2019). "The present study is focusing on the association between the DRD2 gene promoter region polymorphisms and schizophrenia in the northern Chinese Han population." (PMID 30657260, 2019). "The D2 dopamine receptor (Drd2) is implicated in several brain disorders such as schizophrenia, Parkinson’s disease, and drug addiction." (PMID 30604007, 2019). "This study showed that a DRD2 co-expression gene set enriched for protein-coding genes associated with schizophrenia modulates PFC function during working memory and response to D2 antagonist antipsychotics." (PMID 31040787, 2019). "Up till now, most studies related to the association between the promoter region in DRD2 gene and schizophrenia mainly focused on rs1799732." (PMID 30657260, 2019).